CLIC2 (CLIC family member 2)
Description:
In the soluble state, catalyzes glutaredoxin-like thiol disulfide exchange reactions with reduced glutathione as electron donor. Displays weak glutathione peroxidase activity (Probable). Can insert into membranes and form chloride ion channels. Membrane insertion seems to be redox-regulated and may occur only under oxidizing conditions. Modulates the activity of RYR2 and inhibits calcium influx.
Synonyms: XAP121; CLCNL2; CLIC2b; MRXS32
Tractability: Small molecule: a structure with a bound ligand is known. Antibody: its Gene Ontology location is reachable by antibodies, with high confidence; UniProt predicts a signal peptide or a membrane-spanning region; the Human Protein Atlas places it where antibodies can reach. PROTAC: ubiquitination databases record sites on it; its protein half-life has been measured.
Gene: Protein-coding gene on chromosome X (155,276,211 to 155,334,673, reverse strand). Ensembl gene ENSG00000155962.
Subcellular location: Cytoplasm; Membrane
Subcellular location (Human Protein Atlas): Cytosol; Plasma membrane; Nucleoplasm
Pathways (Reactome):
Muscle contraction: Ion homeostasis
Transport of small molecules: Stimuli-sensing channels
Gene Ontology:
Molecular function: glutathione peroxidase activity; glutathione transferase activity; protein binding; chloride channel activity
Biological process: regulation of cardiac muscle contraction by regulation of the release of sequestered calcium ion; regulation of release of sequestered calcium ion into cytosol by sarcoplasmic reticulum; chloride transport; signal transduction; cellular oxidant detoxification; chloride transmembrane transport
Cellular component: cytoplasm; cytosol; plasma membrane; membrane; nucleus
Gene-disease validity (ClinGen):
ClinGen rates the evidence that CLIC2 causes each of these diseases.
X-linked complex neurodevelopmental disorder (X-linked): Disputed. A complex neurodevelopmental disorder that is transmitted via X-linked inheritance, and is characterized by intellectual disability, autism and epilepsy.
Homologues: Orthologues: chimpanzee CLIC2 (100% identical), macaque CLIC2 (98% identical), dog CLIC2 (94% identical), guinea pig CLIC2 (94% identical), rabbit CLIC2 (93% identical), rat Clic2 (92% identical), pig CLIC2 (89% identical), zebrafish clic2 (70% identical), Caenorhabditis elegans exl-1 (29% identical), Drosophila melanogaster Clic (26% identical), Caenorhabditis elegans exc-4 (26% identical), Caenorhabditis elegans gst-43 (15% identical), and 27 more. Paralogues in human: CLIC6 (64% identical), CLIC4 (63% identical), CLIC5 (63% identical), CLIC1 (59% identical), CLIC3 (47% identical), EEF1G (19% identical), GSTT2 (19% identical), GSTT2B (19% identical), GSTO1 (18% identical), GDAP1 (17% identical), GSTZ1 (17% identical), GSTT4 (17% identical), and 2 more.
Diseases named in the same sentence as CLIC2 in open-access papers:
CLIC2 is named in the same sentence as 40 diseases in open-access papers, as found by Europe PMC text mining. Sharing a sentence is not in itself a finding about the gene and the disease. The quoted sentences say what the papers report.
breast carcinoma (3 papers, 2020 to 2023). "CLIC2 is co-expressed with PD-L1/PD-1 in breast cancer and is a biomarker candidate for favorable prognosis." (PMID 37414767, 2023). "lncRNA OIP5-AS1 promotes breast cancer progression by regulating miR-216a-5p/GLO1.CLIC2 is a useful biomarker for identifying breast cancer patients who could benefit from immune checkpoint blockade." (PMID 35224098, 2022). "Survival analysis of CLIC2 mRNA in breast cancer patients (the PrognoScan database)." (PMID 32915772, 2020). "Secondly, CLIC2 was shown to be co-expressed with PD-L1 and PD-1 and act as a good prognosis marker with higher rates of tumor-infiltrating CD8 + T cells in breast cancer patients." (PMID 37414767, 2023).
hepatocellular carcinoma (3 papers, 2020 to 2022). A malignant tumor that arises from hepatocytes. "CLIC2 expression decreased not only in hepatocellular carcinomas but also in colorectal cancer-derived metastatic liver cancers and primary colorectal cancer tissues compared to each surrounding tissue with normal appearance." (PMID 36230813, 2022). "In hepatocellular carcinoma, CLIC2 expression was decreased in cases of advanced stages and/or complicated by liver fibrosis." (PMID 36230813, 2022). "A previous study reported that CLIC2 mRNA expression at the early stage (stage IA) was significantly higher than at advanced stages (stage ≥ IB) in hepatocellular carcinoma tissues." (PMID 32915772, 2020). "In human hepatocellular carcinoma and colorectal cancer cells, CLIC2 was shown to be important in forming tight junctions in the cancer vasculature and could be playing a role in preventing metastasis." (PMID 32116799, 2020). "Expression of CLIC2 and other tight junction proteins such as claudins 1 and 5, occludin and ZO-1 were significantly higher in non-cancer cells as compared to human hepatocellular carcinoma." (PMID 32116799, 2020).
Intellectual disability (3 papers, 2013 to 2020). "Similarly, CLIC2 interacts directly with ryanodine receptors and modulates their activity but does not conduct any ions by themselves, but a missense mutation in CLIC2 causes intellectual disability and cardiomegaly." (PMID 32116799, 2020). "Other X-linked forms of mental retardation have been reported in patients with mutations in GDI1, CLIC2, HCFC1, and RAB39B." (PMID 23634718, 2013).
X-linked intellectual disability (3 papers, 2020 to 2024). An X-linked intellectual deficiency in which not enough information is known, reported or published to indicate whether a gene causes non-syndromic or syndromic presentations. "In a large-scale next-generation sequencing of X-chromosome genes, a mutation in CLIC2 was identified on Xq28 in a male with X-linked intellectual disability (XLID)." (PMID 32116799, 2020). "CLIC2 mutation was identified on Xq28 in a male with X-linked intellectual disability (XLID)." (PMID 32944011, 2020). "Using exome analysis and deep sequencing of genes on the X-chromosome, a mutation in CLIC2 (c.303C>G, p.H101Q) was discovered, which was found to be associated with X-linked intellectual disability (ID), atrial fibrillation, cardiomegaly, congestive heart failure (CHF), and seizures." (PMID 32116799, 2020).
brain tumors (2 papers, 2022 to 2025). "Even in brain tumors, which do not cause distant metastasis, CLIC2 suppresses the invasiveness of the tumor cells into the surrounding brain tissues." (PMID 36230813, 2022).
Cognitive impairment (2 papers, 2015 to 2023). Abnormal cognition is characterized by deficits in thinking, reasoning, or remembering. "The substitution reverses the inhibitory action of CLIC2 on RyR1 and RyR2, so that the H101Q CLIC2 becomes a strong activator of the ion channels and is associated with seizures, cognitive impairment and learning disabilities." (PMID 38203604, 2023). "A missense mutation in CLIC2 was reported in two brothers with cognitive impairment, seizures and cardiac anomalies." (PMID 25927380, 2015). "RAB39B and possibly CLIC2 are the most likely candidate genes in which mutations have been reported in individuals with cognitive impairment." (PMID 25927380, 2015). "From the remaining three genes, loss-of-function mutations in both RAB39B and CLIC2 have been reported in individuals with cognitive impairment making it less likely that the hemizygous loss of these genes results in the lethality in males with int22h1/int22h2-mediated deletion." (PMID 25927380, 2015).
melanoma (2 papers, 2021 to 2023). A malignant, usually aggressive tumor composed of atypical, neoplastic melanocytes. "In short, BST2 is part of an anti-CTLA4 response in melanoma and CLIC2 is a favorable prognosis biomarker." (PMID 38269333, 2023). "In this study, 7 genes (CYTL1, CCL8, FCGR2C, OAS1, HAPLN3, WIPF1, CLIC2) were identified as prognostic signatures for melanoma." (PMID 33428606, 2021).
meningioma (2 papers, 2022). A generally slow growing tumor attached to the dura mater. "Our previous report demonstrated that siRNA-induced CLIC2 knockdown in meningioma cells causes increased MMP-2 expression." (PMID 36672037, 2022). "In meningiomas, CLIC2 was expressed at much higher levels by tumor cells than by blood vessel endothelial cells." (PMID 36230813, 2022). "Primary cultured human meningioma cells, which originally expressed CLIC2 abundantly, showed little invasive activity, but the knockdown of CLIC2 resulted in marked invasion in the Boyden chamber assay." (PMID 36230813, 2022). "Surprisingly, the Western blot analysis of culture supernatants revealed that grade I meningioma cells secreted a significant amount of CLIC2." (PMID 36230813, 2022). "In meningioma cases, the association between progression-free survival (PFS) and CLIC1, CLIC2, and CLIC4 expression levels was examined, and PFS was found to be significantly prolonged only when CLIC2 was highly expressed." (PMID 36230813, 2022). "The most benign grade I meningioma tumors express CLIC2 protein and mRNA at much higher levels than the most malignant grade IV glioblastomas." (PMID 36230813, 2022). "CLIC2 expression was weaker in the rather benign grade I glioma cells than in grade I meningioma cells but still higher than that in grade IV glioblastoma cells." (PMID 36230813, 2022). "A similar correlation was also reported in our previous work with meningioma cells, where MMP-2 expression and cellular invasion were suppressed by the addition of recombinant CLIC2." (PMID 36672037, 2022).
glioblastoma (1 paper, 2022). The most malignant astrocytic tumor (WHO grade IV). "Although the number of patients studied was small, PFS was significantly prolonged in glioblastoma cases when CLIC2 was highly expressed." (PMID 36230813, 2022). "CLIC2 protein was added to the culture medium during an invasion assay with U251 human glioblastoma cell line using the Boyden chamber with Matrigel-coated cell culture inserts." (PMID 36230813, 2022).
glioma (1 paper, 2022). A benign or malignant brain and spinal cord tumor that arises from glial cells (astrocytes, oligodendrocytes, ependymal cells). "Based on the CLIC2 expression level, 10 human glioma stem cell lines were divided into two groups (high and low CLIC2 expression), and RNA-Seq was used to determine the gene expression of each group." (PMID 36230813, 2022). "C6 glioma cells strongly express CLIC4, and it will also be necessary to examine whether the forced expression of CLIC2 and the knockdown of CLIC4 have a synergistic suppressive effect on invasion and metastatic potential." (PMID 36230813, 2022).
mental disorder (1 paper, 2021). A disease that has its basis in the disruption of mental process. "As an example, the variation H101Q in the CLIC2 protein has been associated with a mental disorder and predicted to make the CLIC2 protein thermodynamically more stable and to interact more strongly with the ryanodine receptor, obstructing its transport to the cell membrane." (PMID 33598480, 2021).
Parkinson disease (1 paper, 2022). A progressive degenerative disorder of the central nervous system characterized by loss of dopamine producing neurons in the substantia nigra and the presence of Lewy bodies in the substantia nigra and locus coeruleus. "Considering the driving effects of CLIC2 on microglial invasion activity, we prepared 6-OHDA-treated unilateral Parkinson’s disease models where stratal dopamine content was decreased on the ipsilateral side (p < 0.0001, contralateral side)." (PMID 36672037, 2022).
prostate carcinoma (1 paper, 2017). A carcinoma that arises from epithelial cells of the prostate gland. "Very little is known about the functional properties of these two genes, this could make ARMCX1 and CLIC2 the possible candidates of medical relevance, such as prostate cancer in male and oxidative stress-related diseases for female." (PMID 29110633, 2017).
Sepsis (1 paper, 2023). Sepsis is defined as life-threatening organ dysfunction caused by a dysregulated host response to infection. "The genes TPSO, CYP1B1, LCN2, CLIC2, and ELL2 were up-regulated and FTO was down-regulated in sepsis compared to the uncomplicated infections (p < 0.05)." (PMID 36820206, 2023).
skin cancer (1 paper, 2023). "Of the five MOBILE-hypothesized connector genes (BST2, CLIC2, FAM83D, ACSL5, and HIST2H2AA3) between IRF1 and PD-L1, BST2 was recently recognized as part of an immune/tumor-related signature that is significantly associated with the overall survival of skin cancer patients." (PMID 37414767, 2023).
cancer (13 papers, 2015 to 2024). A tumor composed of atypical neoplastic, often pleomorphic cells that invade other tissues. "Although this provided no direct evidence that high CLIC2 mRNA level was associated with enriched TILs, cancer blood vessels with CLIC2 high expression imply relative intact function of blood vessels in the initial stage cancer." (PMID 32915772, 2020). "CLIC2 was found to be expressed at higher levels in benign tumors than in malignant tumors, most likely preventing tumor cell invasion into surrounding tissues." (PMID 38571962, 2024). "Studies on human cancer suggest that CLIC2 inhibits hematogenous metastasis by strengthening adhesions between vascular endothelial cells, and similar results have been obtained in a rat model of distant metastasis." (PMID 36230813, 2022). "Alternatively, CLIC2 was expressed by blood vessel endothelial cells in the normal tissues surrounding cancer tissues and CD11b-expressing myeloid leukocytes, primarily the monocyte/macrophages and fibroblast-like cells in the cancer stroma." (PMID 36230813, 2022). "Generally, CLIC4 exerts detrimental effects on cancer progression, while CLIC2 shows ameliorative effects." (PMID 36230813, 2022). "The findings from databases on survival and CLIC2 expression in gastric and lung cancer are compatible with these clinical data on brain benign and malignant tumors." (PMID 36230813, 2022). "It is crucial to investigate new CLIC2-based therapies for malignant tumors because the increased expression of CLIC2 can prevent the metastatic invasiveness and distant metastasis of malignant tumors." (PMID 36230813, 2022). "In this review, we focus on CLIC2, which has received less attention than other CLICs, and discuss its role in the metastasis and invasion of malignant tumor cells." (PMID 36230813, 2022). "A mechanistic study of CLIC2 functions in human cancer tissues demonstrated that, apart from chloride transport, CLIC2 is involved in tight junction formation." (PMID 35743818, 2022). "Western blot yielded comparable results, showing higher CLIC2 protein expression in normal tissues than in cancer tissues." (PMID 36230813, 2022). "CLIC2 is reportedly involved in the formation and/or maintenance of tight junctions, which allows the intravasation of cancer cells." (PMID 33759378, 2021). "Although CLIC2 was shown to be significant expressed in non-cancer tissues in studies of human hepatocellular and metastatic colorectal carcinomas 33, we found CLIC2 not to be differentially expressed in ESCC versus NT groups." (PMID 32328183, 2020). "Ablation of CLIC2 in human umbilical vein endothelial cells (HUVECs) compromised the integrity of the vessels and allowed human cancer cells to transmigrate through a HUVEC monolayer." (PMID 32116799, 2020). "These keys findings implicate CLIC2 in the formation or maintenance of tight junctions which the cancer cells lack." (PMID 32116799, 2020). "When BC cases were divided by clinical signatures (tumor size or disease stages), CLIC2 mRNA level in small tumor or early-stage cancer tissue was significantly higher than that in larger tumor or advanced-stage cancer tissue, respectively." (PMID 32915772, 2020). "CLIC2 was also expressed in vascular endothelial cells of normal tissues and maintains their intercellular adhesive junctions, presumably suppressing hematogenous metastasis of malignant tumor cells." (PMID 38571962, 2024). "Such differential expression of CLIC2 at the cellular level may be responsible for the differences in CLIC2 expression levels between normal and cancer tissues." (PMID 36230813, 2022). "CLIC2 is also expressed in the vascular endothelial cells of normal tissues and maintains their intercellular adhesive junctions, presumably suppressing the hematogenous metastasis of malignant tumor cells." (PMID 36230813, 2022). "In cancer tissues, scarce CLIC2 expression may lead to unstable intercellular adhesion, enabling the hematogenous spread of malignant cells." (PMID 36230813, 2022).